HIF1A (hypoxia inducible factor 1 subunit alpha)
Diseases named in the same sentence as HIF1A in open-access papers (continued):
Sharing a sentence is not in itself a finding about the gene and the disease.
infection (continued). "The viral ORF3a protein is shown to increase the production of HIF-1α during SARS-CoV-2 infection, which in turn promotes the inflammatory responses and subsequently the infection." (PMID 38049897, 2023). "To further explore this relationship, we measured parameters of mitochondrial respiration as extensions of the effects of infection and DMOG treatment on HIF-1α stabilization." (PMID 37417946, 2023). "Immunoblot studies showed an elevation in protein levels of HIF1-α, TLR-2, and EGFR long-term post-MHV-1 infection." (PMID 37626956, 2023). "Treatment with a synthetic peptide, SPIKENET (SPK), which inhibits spike protein binding, reduced NGAL mRNA in acute infection, and decreased TGF-β1, BCL3 mRNA, EGFR, HIF1-α, and TLR-2 protein levels long-term post-MHV-1 infection." (PMID 37626956, 2023). "Referring to HIF1α and its inhibitor PHD2, it is well known that expression of the first factor is activated by the parasite in the early stages of infection and it plays a fundamental role in favoring T. gondii multiplication." (PMID 36185508, 2022). "Filaggrin, HIF-1α, VEGF, RANTES/CCL5, IL-17A, IL-1β, MIP-1α and MIP-1β/CCL5 levels were higher during and after infection." (PMID 36482106, 2022). "Four hours of infection with the wild-type and the T4SS mutant (ΔdotA) similarly augmented hypoxia-induced HIF1α stabilization." (PMID 35755850, 2022). "In particular, as a target of HIF-1α, lactate dehydrogenase (LDH) activity is elevated in macrophages upon infection to catalyze the conversion of pyruvate into lactate." (PMID 37073169, 2022). "We found cytokines like IFNγ, IL-4, IL-13, IFNβ1, TNFα, and transcriptional regulators such as HIF1α, STAT1, CTCF, TP73, IRF1, MXD1, ATF4, SPI1 mediate macrophage activation upon infection." (PMID 35789215, 2022). "ART-treated infection impacted the metabolic fraction (with elevated expression of PPARγ and CEBPα), the extracellular matrix (with elevated expression of COL1A2 and HIF-1α), and the inflammatory profile." (PMID 36231066, 2022). "Lungs of Vhl Hif1a dcKO and WT mice also showed similar frequencies of central and effector memory CD4 and CD8T cells at 4 and 7 weeks after infection." (PMID 36064840, 2022). "We found that Ms_Rv0580c up-regulated the HIF-1α expression in macrophages via the NF-κB/JNK axis, indicating the role of Rv0580c in the host defense against infection." (PMID 33535567, 2021). "Moreover, HIF-1α could promote broadly the infections of other viruses." (PMID 34408131, 2021). "Our results revealed that infection with B. abortus boosts the basal and compensatory glycolysis in HIF-1α WT and HIF-1α KO macrophages." (PMID 33989349, 2021). "We detected the up-regulation of HIF-1α expression in Ms_Rv0580c infected THP-1 macrophages, as compared to Ms_pNIT infected THP-1 macrophages, at 6 h and 24 h post-infection." (PMID 33535567, 2021). "At all doses of MCMV, splenic NK cell activation was observed on day 1.5 post-infection (pi) as indicated by CD69 expression, an activation marker not expressed on naïve NK cells, and concomitant with increased HIF1α expression." (PMID 34396954, 2021). "The mRNA expression of HIF-1α was significantly up-regulated both in MEE and cells of MELF at day 1 post-infection compared to PBS control, consistent with the expression levels of glycolysis-related genes." (PMID 33953708, 2021). "Macrophages were exposed to 0.1 or 0.2 mM DMOG prior to infection, and the expression of VEGF-A, which can result from HIF-1α or HIF-2α activation, was examined by real-time PCR." (PMID 34959539, 2021). "On one hand, six of these biomarkers (CD14, HVEM, IL-6, B7.1, Siglec-10, and HIF-1α) were related to both HIV exposure and infection, presenting significantly higher expression in both the HIV+ and HEU groups than in the UU group." (PMID 34211989, 2021).
infection (continued). "Quantification of HIF1α protein levels, after normalization to tubulin protein levels, was done in cells infected with TB40/E at a multiplicity of infection (MOI) of 3 infectious units per cell." (PMID 33758082, 2021). "Mechanistically, this metabolic reprogramming was induced by STING-dependent stabilization of hypoxia-inducible factor-1 alpha (HIF-1α), and HIF-1α signaling enhanced glycolytic metabolism and diminished OXPHOS upon infection." (PMID 35011636, 2021). "As HIF-1α promotes SARS-CoV-2 replication and is induced upon infections of various viruses including SARS-CoV-2, VSV, and HSV-1, and thus, we determined the effect of HIF-1α on the infections of other viruses." (PMID 34408131, 2021). "During L. major infection in vivo, HIF-1α and HIF-2α, as well as multiple HIF-1α and HIF-2α targets, including Vegfa, Nos2, and Arg1, are elevated at the site of infection." (PMID 34959539, 2021). "These conditions in conjunction with L. major infection in macrophages mimic the hypoxic environment and the elevated HIF-1α and HIF-2α expression present at the site of infection in leishmanial lesions." (PMID 34959539, 2021). "We thus demonstrate paracellular migration of bacteria across BBB and a critical role for HIF-1α/VEGF therein and hence propose targeting this pathway to prevent BBB dysfunction and ensuing brain damage in infections." (PMID 32529267, 2020). "Of note, Mtb infection induces the increase of HIF-1α expression in IFN-γ-activated macrophages (M1), which is essential for IFN-γ-dependent control of infection." (PMID 33002063, 2020). "Inhibition of Nrf2 by lentiviral infection of Keap1, or knockout of Nrf2 by CRISPR-Cas9 gene editing, not only blocked iAs-induced HIF1α activation, but reduced the expression of the key stemness genes for the formation of CSCs also." (PMID 32226544, 2020). "RAW 264.7 cells were cocultured with H. pylori at various multiplicities of infection (MOIs), and iNOS, CD86, Arg-1, CD206, and HIF-1α expression was detected by Western blot, PCR, and ELISA analyses." (PMID 33376580, 2020). "In our study, we found RSV infections in SAE and iSAE cells to stabilize both HIF-1α and HIF-2α following infection." (PMID 32993138, 2020). "The transcription factor Hif1α is a major regulator of innate immunity against pathogens and macrophage INF-γ-dependent control of infection." (PMID 33255176, 2020). "The downregulation of HIF-1α expression by ROS savenger and HIF-1α inhibitor or knockdown by lentiviral shRNA infection diminished NiCl2-activated ANGPTL4 expression." (PMID 31963541, 2020). "The decrease in HIF-1α mRNA availability and concomitant down-regulation of HIF-target genes indicated that EnAd infection suppresses HIF-1α mRNA transcription, thereby decreasing the accumulation of HIF-1α protein during hypoxic culture." (PMID 32244697, 2020). "These factors are critical for virulence and, during infection, induce secretion of interleukin-6, CXCl1, and CXCL2, assist with bacterial dissemination to the spleen, and stabilize hypoxia inducible factor-1a (HIF-1a)." (PMID 32390954, 2020). "In order to rule out any confounding effects due to the long-term impact of HIF1α exon 2 deletion in Null cells, we carried out two alternative approaches to inhibit HIF1 activity during MHV68 lytic infection." (PMID 31809522, 2019). "It was revealed that HIF-1α and VEGF mRNA levels were upregulated at 4 days after Lenti-miRNA-21 infection." (PMID 30795815, 2019). "HIF1α wild-type (WT) and Null MEFs were infected with high and low MOI of MHV68 virus, viral supernatants were harvested at different times post-infection (dpi), and amount of infectious virus was determined by plaque assay." (PMID 31809522, 2019). "p-SLC34A2 infection increased the expression of HIF-1α and EZH2, indicating that SLC34A2 lies on the upstream of HIF-1α and EZH2." (PMID 30038060, 2019).
infection (continued). "When HIF-1α was knocked-down by adding HIF-1α-shRNA-2 lentivirus, the enhancement of expression of SLC2A1 (GLUT1) and PDK1 by infection with the wild-type EPEC E2348/69 strain was diminished." (PMID 30125331, 2018). "Both in A549 and THP-1 cells, the cytoplasmic HIF-1α level declined and the nuclear HIF-1α level increased from 12 to 36 h post infection (P<0.05)." (PMID 28536432, 2017). "The stably transfected clones AGS sh-HIF-1α C7 and AGS sh-Scr C2 were chosen for infection by H. pylori 26695 at MOI 100 for 24 h and induction of mRNA of several HIF-1α target genes were evaluated." (PMID 28401064, 2017). "In summary, we found that FV infection leads to increased spleen weights in HIF-1α+f/+f (WT) and HIF-1α+f/+f × LysM-Cre (KO) mice after 7 days, but the infection leads to massive erythroblast proliferation in WT mice only." (PMID 29222473, 2017). "Infection with H. pylori CagA induced downregulation of SIRT3 protein in mitochondria, stimulated ROS production, and elicited HIF-1α stabilization with increased transcriptional activity, similar to that observed during hypoxia." (PMID 29108235, 2017). "We have also previously shown that HIF-1α is required for host protection against IPA, due to inefficient neutrophil recruitment at the site of infection." (PMID 27651366, 2016). "However, HIF-1α may be a key factor for Mtb infection control, as mice lacking HIF-1α in the myeloid lineage were more susceptible to infection and exhibited defective production of inflammatory cytokines and microbicidal effectors." (PMID 28018344, 2016). "Previously we showed that early after infection, VACV protein C16 induces stabilization of HIF-1α by inhibiting the enzymatic activity of PHD2." (PMID 25351724, 2015). "Microarray gene expression was confirmed by real-time quantitative PCR for a subset of12 genes, which revealed that IFNG HIF1A and TNFA, among others, were significantly differentially expressed between the two strains at day 14 post-infection." (PMID 23006927, 2012). "Reduction in comparable growth rate at 24 h compared to 12 h was probably due to normal HIF-1 activation by LD-infection in untransfected and wild-HIF-1α transfected cells that limited the advantage of HIF-1α over-expression." (PMID 22701652, 2012). "HIF-1α transcription is detected as an essential mechanism of HIF-1 activation in response to inflammation and infection." (PMID 22701652, 2012). "Such infection led to a robust HIF-1 activation and HIF-1 dependent VEGF induction shown by HIF-1α-immunoblotting, HIF-1-dependent luciferase reporter assays and quantitative PCR analysis." (PMID 20644645, 2010). "After having demonstrated HIF-1α protein stabilization during infection with RSV, we next pursued functional consequences of HIF-1α in transcriptional gene induction during RSV infection." (PMID 18839041, 2008). "The elevation of HIF-1α expression was consistent with the upregulation of HIF-1α target genes, including GLUT1 and LDHA, observed in PEDV-infected cells, supporting the involvement of HIF-1α in glycolytic activation during infection." (PMID 41512444, 2026). "Expression of HIF1A and ENTPD support that the sites of injury and infection are hypoxic." (PMID 39882906, 2025). "The positive correlations observed between HIF-1α, HIF-2α, and P4H-TM in these patients imply that these markers may work together in the inflammatory and hypoxic response induced by the infection." (PMID 40731804, 2025). "Additionally, we found that pimonidazole (Hypoxyprobe) staining and HIF-1α expression increased in leukocytes (CD45+) and T cells (CD3+) from cardiac tissue after infection." (PMID 40590226, 2025). "Similarly, expression of GBP1, NLRP3, and IL1B was downregulated in both HIF1‐KD and GBP1‐KD macrophages, while expression of ASC1 and HIF1A was upregulated in HIF1‐KD and GBP1‐KD macrophages, respectively, upon H37Rv infection, compared with controls." (PMID 41287823, 2025).
infection (continued). "Biomarkers for HIF-1α, HIF-2α, and P4H-TM show potential in distinguishing H. pylori-positive patients due to their roles in hypoxia and inflammation pathways activated during infection." (PMID 40731804, 2025). "In support of this data, through pathway analysis, we have shown that in vitro, the HIF-1α signaling pathway is enriched during infection with L. major and many initial transcriptomic changes are HIF-α-dependent suggesting infection with L. major initiates the HIF-α transcriptional program." (PMID 40191198, 2025). "In addition, the expression of HIF-1α and PAD4 was upregulated in GES-1 cells following infection with H. pylori for 6 hours in an MOI-dependent manner." (PMID 39107082, 2024). "Studies on mice lacking HIF-1α in immune cells assessed the impact of infection and inflammation on the immune system." (PMID 39456823, 2024). "Treating the reporter cells with three PHIs (Daprodustat, Molidustat and Roxadustat) induced GFP expression in a time-dependent manner, whereas infection with RSV failed to activate GFP expression or to stablise HIF-1α expression." (PMID 38261926, 2024). "HIF1A gene limits the microbicidal ability of myelocyte-derived cells and, in macrophages, HIF1A seems to play a fundamental role in survival of L. donovani at late phase (30 hours p.i.), but not at an earlier stage (6 hours p.i.)of infection." (PMID 39028711, 2024). "Pretreatment of HSAEC1-KT cells with 25 μM gefitinib (a potent inhibitor or EGFR signaling), did not alter infection-induced accumulation of HIF1α." (PMID 38902255, 2024). "Taken together, these results support the idea that the HIF1α pathway is activated during infection of epithelial cells by Mucorales and this activation is not a strain- or species-specific phenomenon." (PMID 38902255, 2024). "The expression of HIF1α transcript did not change over the first 3 h of the infection and decreased by 6 h post-infection indicating that the increase in protein accumulation was not a simple result of increased HIF1α mRNA production." (PMID 38902255, 2024). "In vitro and in vivo experiments further identified the transcription factors nuclear factor of activated T cell 1 (NFATc1) and hypoxia-inducible factor 1 alpha (HIF-1α), which are activated by calcium-dependent phosphatase calcineurin and lead to IL-33 production during infection." (PMID 38750790, 2024). "In addition to HIF-1α, IFN-1 mediates macrophage reprogramming during this infection, and STING mainly mediates this." (PMID 38312740, 2024). "Moreover, cytokines released by immune cells post-infection, including IL (interleukin) -6, -4, -12, -1, and tumor necrosis factor alpha (TNF-α), can contribute to the increased expression of HIF-1α." (PMID 38539163, 2024). "In extrapulmonary pleural TB, inhibition of HIF-1α and changes in macrophage phenotype from glycolysis to OXPHOS resulted in attenuation of microbicidal properties of infected macrophages and the consequent failure to restrict infection." (PMID 38045029, 2023). "Regarding the mRNA expression, a significant increase in TGF-β1, HIF-1α, NGAL, B2M, FGF23, TLR-2, IL-18, and YKL-40 was observed in the long-term post-MHV-1 infection, whereas only NGAL was found to be significantly increased in the acute stage post-infection." (PMID 37626956, 2023). "This feature allowed for examination of HIF-1α–mediated effects on infection independent of its reported role on viral uptake, specifically with respect to metabolic outcomes." (PMID 37417946, 2023). "Therefore, the HIF1A-LDHA pathway, regulated by GABRA4 signaling, is involved in activating autophagy and antimicrobial host defense during infection." (PMID 40395295, 2023). "In contrast, the expression of the TJ protein ZO-1 in HIF-1α knockdown cells did not decrease as much after infection." (PMID 36916939, 2023).
infection (continued). "In parallel, positive regulators, such as HIF-1α, a master transcriptional regulator of glycolysis, and IGFBP5, capable of activating IGF1R-AKT to increase glycolysis, were significantly upregulated post infection." (PMID 37256871, 2023). "Aerobic glycolysis promotes the activity of the transcription factor hypoxia-inducible factor 1α (HIF-1α), especially in IFN-γ-activated macrophages, and macrophages lacking HIF-1α are defective in the IFN-γ-mediated control of infection." (PMID 36297211, 2022). "We focused on hypoxic conditions, as, under normoxia, HIF1α is degraded starting at 24 h post-infection regardless of the pathogen viability." (PMID 35755850, 2022). "During and after infection, a further increase in VEGF and HIF-1α was observed, which may reflect enhanced angiogenesis, and possible are also related to the homeostasis of oxygen during lung infections." (PMID 36482106, 2022). "As LD formation is uncoupled from control in both contexts, it is likely that the antibacterial effects of HIF-1α activation are related during IFN-γ- and GM-CSF-mediated control, although how HIF-1α activation leads to macrophage control of infection remains an open question." (PMID 35877763, 2022). "Furthermore, SGLT1 transcription was increased in the jejunum of both infection groups, while transcription of GLUT1 and Hif-1α was upregulated in the trickle-infected group at 21 dpi." (PMID 34649607, 2021). "Although this occurs rather inefficiently due to the absence of ACE2 expression, infection can be increased by hypoxia and its downstream upregulation of a glycolytic metabolism by hypoxia inducible factor 1alpha (Hif1α)." (PMID 34867933, 2021). "MFN2 did not impact mitophagy during infection; however, it promoted xenophagy activation through HIF-1α." (PMID 33972668, 2021). "In line with this, the stabilization of HIF1α in bacterial dermatitis via lack of oxygen and/or infection itself resulted in the production and secretion of antibacterial peptides and pro-inflammatory cytokines (reviewed:)." (PMID 33125509, 2021). "Here, we identify the tricarboxylic acid (TCA) cycle metabolite fumarate as the driver of IL-10 during macrophage infection with H. capsulatum in the absence of HIF-1α." (PMID 34749531, 2021). "We expanded on this observation by determining if HIF1α protein levels are affected by infection with the TB40/E strain, which has not been extensively passaged in fibroblasts." (PMID 33758082, 2021). "Here we provide evidence that the absence of HIF1α affects survival in NK cells during a pathogen infection." (PMID 34396954, 2021). "For instance, the Newcastle disease virus (NDV) has been described to downregulate HIF-1α through its targeting to the proteasomal pathway and inhibit HIF-1α protein accumulation in various cell lines upon infection, overall producing a decrease in the transcription of HIF-1-target genes." (PMID 34360716, 2021). "Furthermore, the infections led to an induction of VEGF, a known target gene of HIF-1α transcriptional activity." (PMID 32529267, 2020). "In contrast, similar infection of gp91phox−/− mice did not increase the numbers of BM HIF-1α+ neutrophils as observed in WT counterparts." (PMID 32669546, 2020). "Our studies have shown that deletion of HIF-1α or inhibition of mammalian target of rapamycin (mTOR; known to stabilize HIF-1α) attenuates MPLA-induced increased glycolysis, abolishing the protective effect of MPLA against infection." (PMID 33679711, 2020). "The infection of AGS cells with three different chloramphenicol resistant clones revealed that CagA was not essential for HIF-1α induction as revealed by the Western blot and luciferase reporter assays." (PMID 31185594, 2019). "In our study, we show that stabilization of Hif-1α upregulates proinflammatory macrophage il-1β expression in the absence of an infection challenge." (PMID 30552162, 2019).